SETDB1 (SET domain bifurcated histone lysine methyltransferase 1)
Diseases named in the same sentence as SETDB1 in open-access papers (continued):
Sharing a sentence is not in itself a finding about the gene and the disease.
glioblastoma (7 papers, 2015 to 2024). The most malignant astrocytic tumor (WHO grade IV). "Furthermore, in glioblastoma (GBM), the nuclear expression levels of lysine methyltransferases, such as SETDB1, KMT5B, Suv-39h1, and EZH2, are elevated and associated with advanced histological cancer grades." (PMID 39620228, 2024). "These indicated that TRAF4 promoted glioblastoma proliferation, at least in part, by regulating SETDB1 stability and function." (PMID 36077559, 2022). "We performed protein turnover assays and the results suggested that TRAF4 knockdown can effectively reduce the stability of SETDB1 in glioblastoma cells treated with de novo protein synthesis inhibitor cycloheximide (CHX)." (PMID 36077559, 2022). "Further immunoprecipitation experiments in glioblastoma cells showed that endogenous TRAF4 likewise interacted with SETDB1." (PMID 36077559, 2022). "Restoring SETDB1 expression in TRAF4 knockdown glioblastoma cells partially restored cell growth and proliferation." (PMID 36077559, 2022). "The results of Western blot showed that the SETDB1 expression was also decreased following TRAF4 knockdown in glioblastoma cells." (PMID 36077559, 2022). "To further confirm that TRAF4 promoted glioblastoma proliferation through regulating the stability and function of SETDB1, we overexpressed SETDB1 in TRAF4 knockdown glioblastoma cells." (PMID 36077559, 2022). "We examined the mRNA expression of SETDB1 in glioblastoma cells to exclude the effect of reduced mRNA on SETDB1 protein expression." (PMID 36077559, 2022). "Immunoprecipitation experiments showed that both TRAF4 and SETDB1 interacted with AKT1 in glioblastoma cells." (PMID 36077559, 2022). "EdU incorporation experiments also indicated that the proliferative capacity of TRAF4-knockdown glioblastoma cells was significantly increased following SETDB1 overexpression." (PMID 36077559, 2022). "As the results showed, the SETDB1 expression was also increased following restoring TRAF4 expression in glioblastoma cells." (PMID 36077559, 2022). "Taken together, our experimental results suggested that overexpression of SETDB1 can restore the proliferation of TRAF4 knockdown glioblastoma cells to a certain extent." (PMID 36077559, 2022). "The colony formation assays suggested that overexpression of SETDB1 in TRAF4-knockdown glioblastoma partially restored cell growth." (PMID 36077559, 2022). "Similarly, we examined the intracellular AKT pathway, and the results of Western blot showed that overexpression of SETDB1 in TRAF4-knockdown glioblastoma restored the activation of AKT pathway." (PMID 36077559, 2022). "Firstly, we validated the interaction of TRAF4 and SETDB1 with AKT1 in glioblastoma cells." (PMID 36077559, 2022). "We hypothesized that TRAF4 and SETDB1 are co-involved in the activation of the AKT pathway in glioblastoma based on previous results." (PMID 36077559, 2022). "Taken together, our study characterizes TRAF4 in glioblastoma and demonstrates that the E3 ubiquitin ligase TRAF4 can activate the AKT pathway by stabilizing the expression of SETDB1, ultimately promoting glioblastoma proliferation." (PMID 36077559, 2022). "In the present investigation, we demonstrate for the first time that the expression of these two transcriptionally repressive HKMTs is up-regulated in astrocytic tumors with glioblastomas displaying elevated cytoplasmic SUV39H1 and SETDB1, but intriguingly lower nuclear SUV39H1." (PMID 25602259, 2015). "Intriguingly, Trametinib appeared to specifically reduce ZNF263 protein levels without altering those of KAP1, SUV39H2, EED, or SETDB1, implying that the activation of EGFR/MAPK led to SIX3 silencing in glioblastoma mainly through the regulation of ZNF263." (PMID 32051553, 2020).
inflammatory bowel disease (7 papers, 2020 to 2025). A spectrum of small and large bowel inflammatory diseases of unknown etiology. "Setdb1 deficiency causes constitutive expression of rTEs in inflammatory bowel disease, and overexpression of Setdb1 in cancers improves immune evasion by restricting expression of rTE-encoded proteins." (PMID 40339988, 2025). "Aberrant activity of SETDB1 has also been implicated in several neuropsychiatric, cardiovascular and gastrointestinal diseases, including schizophrenia, Huntington’s disease, congenital heart defects and inflammatory bowel disease." (PMID 34440561, 2021). "Rare missense variants of SETDB1 have been identified in Inflammatory Bowel Disease (IBD) patients and are associated with its pathogenesis." (PMID 34440561, 2021). "Current studies have shown that H3K9 is the main substrate of SETDB1, and SETDB1 regulates multiple biological processes (e.g., embryonic stem cell and aging) and various diseases (e.g., tumors and inflammatory bowel disease) by tri-methylating H3K9." (PMID 38057834, 2023). "Accordingly, SETDB1 is downregulated in patients with inflammatory bowel disease (IBD)." (PMID 33050394, 2020). "Activation of ZBP1 by endogenous retroviruses (ERV) is also reported in human inflammatory bowel disease (IBD) patients, possibly due to low expression levels of the repressive methyltransferase SETDB1." (PMID 32742689, 2020). "Additionally, SETDB1 is engaged in regulating multiple biological processes and diseases, such as ageing, tumors, and inflammatory bowel disease (IBD), by methylating both histones and non-histone proteins." (PMID 38057834, 2023).
leukemia (7 papers, 2020 to 2026). A malignant (clonal) hematologic disorder, involving hematopoietic stem cells and characterized by the presence of primitive or atypical myeloid or lymphoid cells in the bone marrow and the blood. "The H3K9 methyltransferase SETDB1 has been reported to play a tumor suppressor role by limiting the expression of genes targeted by MLL1 fusion proteins, contraindicating SETDB1 inhibition in the treatment of MLLr leukemias." (PMID 39403928, 2024). "Concomitantly, deletion of Atf7ip or Setdb1 derepresses retrotransposons, thereby inhibiting human leukemia cell growth and inducing myeloid differentiation and inflammation by activating the viral sensor Mda5/Rig-I like receptor signaling." (PMID 38057834, 2023). "In consistent with this, our observation of the role of Suv39h1 in suppression of MLL-AF9 leukemia progression were in agreement with recent publication which reported a suppressive role of Setdb1 in MLL-fusion induced AML." (PMID 33037410, 2020). "A role for SETDB1 was also recently observed at centromeres in K562 leukemia cells." (PMID 41291334, 2025). "Moreover, SETDB1 maintains hematopoietic stem cells, restricting the activation of non-hematopoietic genes in normal conditions while, when deregulated, it enables leukemia cells to evade innate immune controls allowing them to expand." (PMID 32471360, 2020).
prostate carcinoma (7 papers, 2015 to 2021). A carcinoma that arises from epithelial cells of the prostate gland. "Furthermore, levels of SETDB1 have been recently associated with prognosis and the development of bone metastases from prostate cancer." (PMID 29888169, 2018). "Overexpression of SETDB1 was detected in prostate cancer in clinical and preclinical studies, and the cancer phenotype was suppressed by siRNA in SETDB1 knockdown cells." (PMID 31768101, 2019). "For CpGs with lower methylation in the prostate cancer tissues in comparison with the adjacent-unaffected tissue, there were two TFs with significant overlap that were bound in these regions: FOXA2 and SETDB1." (PMID 28412973, 2017).
schizophrenia (7 papers, 2017 to 2023). A major psychotic disorder characterized by abnormalities in the perception or expression of reality. "In addition, SETDB1 has been implicated to play a role in the aetiology of Schizophrenia by regulating GRIN2B expression." (PMID 33263776, 2021). "Moreover, SETDB1 may disrupt the chromatin contacts associated with schizophrenia risk loci." (PMID 36979236, 2023). "SETDB1 plays a major role in the pathogenesis of several neuropsychiatric disorders, such as schizophrenia and autism spectrum disorder, as well as in neurodevelopmental diseases." (PMID 34440561, 2021). "Additionally, males with schizophrenia were shown to exhibit increased H3K9me2, which was correlated with elevated expression of SETDB1 and G9α methyltransferases." (PMID 38139167, 2023). "Furthermore, a more recent study revealed increased H3K9me2 in the parietal cortex of schizophrenia patients, accompanied by elevated activity of two enzymes, GLP and SETDB1, that catalyze this modification." (PMID 38139167, 2023). "The function of SETDB1, a histone methyltransferase specifically methylating H3K9, and a histone modification involved in transcriptional repression and local heterochromatin formation is also affected in schizophrenia." (PMID 36979236, 2023).
Huntington disease (6 papers, 2020 to 2025). Huntington disease (HD) is a rare neurodegenerative disorder of the central nervous system characterized by unwanted choreatic movements, behavioral and psychiatric disturbances and dementia. "SETDB1 has also been implicated in the pathophysiology of a series of genetic diseases, such as Huntington’s disease (HD) and Rett, Prader–Willi and Cockayne syndromes." (PMID 34440561, 2021). "SETDB1 (ESET) was found to upregulate the level of H3K9me3 in the striatum, which consequently decreased the expression of EGR1, ultimately causing impaired neurological function in the striatum in an R6/2 mouse model of Huntington's disease, resulting in various behavioral deficits." (PMID 39656495, 2024). "A recent study has discovered that SETDB1 (ESET) inhibitors decreased H3K9me3 levels, and improved motor function and neuropathological symptoms in Huntington's chorea transgenic mice." (PMID 39656495, 2024).
lung adenocarcinoma (5 papers, 2014 to 2024). A carcinoma that arises from the lung and is characterized by the presence of malignant glandular epithelial cells. "Clear correlation is observed for the H3K9 trimethylase SETDB1, significantly amplified and overexpressed in 16% of lung adenocarcinoma samples." (PMID 25484917, 2014). "The relative amplification of the genes varied substantially across the cancer types, with SETDB1 amplified in 20% of lung adenocarcinomas, NSD3 amplified in 21% of lung squamous cancers, and BRD4 amplified in 17% of ovarian serious adenocarcinomas." (PMID 24874471, 2014). "On the contrary, highly metastatic lung adenocarcinomas exhibit decreased SETDB1 activity, suggesting that SETDB1 may act as a key oncogene only in the initial stages of NSCLC." (PMID 34440561, 2021).
osteosarcoma (5 papers, 2021 to 2025). A usually aggressive malignant bone-forming mesenchymal neoplasm, predominantly affecting adolescents and young adults. "Given its involvement in osteoblastogenesis and adipogenesis, we discuss the potential of SETDB1 as a key target for new therapeutic strategies in osteosarcoma." (PMID 39945463, 2025). "Through the epigenetic regulation of GRIK2, a known tumor-suppressor gene identified in gastric cancer, SETDB1 appears to enhance cell proliferation, migration, and apoptosis resistance in osteosarcoma." (PMID 39945463, 2025). "To date, very few studies describe the role of SETDB1 in sarcomas, and in osteosarcoma specifically, despite genetic analyses suggesting its involvement in osteosarcoma pathophysiology." (PMID 39945463, 2025). "Both ligases can be activated by the methyltransferase SET domain bifurcate 1 (SETDB1), which is overexpressed in osteosarcoma and that enhances the AKT signaling." (PMID 38534381, 2024). "We also found that SETDB1 protein was mainly localized in the nucleoplasm of A-431 (human epithelial carcinoma cell line), U-2 OS (human osteosarcoma cells), and U-251 MG (human brain glioblastoma astrocytoma cancer cells) and vesicles of U-2 OS cell lines." (PMID 35656340, 2022). "This deletion, therefore, results in overexpression of the anti-oncogenic GRIK2, apoptosis and decreased proliferation and migration while also revealing a possible tumorigenic role of SETDB1 in osteosarcomas." (PMID 34440561, 2021). "In this work, we will discuss the role of SETDB1 in the healthy state, in mesenchymal differentiation, and how its amplification may contribute to the plasticity and immune escape of osteosarcoma cells." (PMID 39945463, 2025). "Thus, targeting SETDB1 in osteosarcoma would represent a potential therapeutic strategy, as it would downregulate both SKP2 and TRAF4 (and their ability to activate AKT)." (PMID 38534381, 2024). "However, downregulation of SETDB1 was also found in metastatic lung cancer, less aggressive osteosarcomas and AML, indicating a tumour suppressive role of SETDB1 in different cancer types and stages." (PMID 34299035, 2021). "However, the downregulation of SETDB1 in metastatic lung cancer, less aggressive osteosarcomas and AML indicates SETDB1 is acting as a tumour suppressor." (PMID 34299035, 2021). "The identification of a SETDB1 inhibitor could provide new hope for the treatment of osteosarcoma by modulating its anti-tumor immune activity and altering its microenvironment, potentially enhancing tumor sensitivity to therapeutic approaches, such as radiotherapy." (PMID 39945463, 2025).
breast tumors (4 papers, 2016 to 2025). "RNA-seq analyses showed that SETDB1/PELP1-regulated genes overlap, with respect to ER signaling, tamoxifen resistance, and PI3K–Akt signaling, suggesting that cytoplasmic localization of PELP1 in breast tumors may enhance SETDB1’s oncogenic functions." (PMID 41463382, 2025). "Our data suggests that SETDB1-PELP1 interactions play a key role in endocrine resistance and that the PELP1 localization to the cytoplasm, commonly seen in breast tumors, may play a role in enhancing SETDB1 oncogenic signaling." (PMID 35395812, 2022). "From a functional standpoint, SETDB1 knockdown inhibited breast tumor growth in vitro and in vivo." (PMID 30309377, 2018).
colon cancer (4 papers, 2016 to 2023). "While it was demonstrated in colon cancer cells that the canonical Wnt pathway recruits Setdb1 at Wnt target gene promoters for transcriptional repression, we uncovered a novel mechanism of Wnt-mediated gene activation by subcellular redistribution of Setdb1." (PMID 27790377, 2016). "Induction of Notch1 transformed high-grade adenoma into low-grade adenoma in an APCMin mouse model of colon cancer and suppressed the expression of Wnt target genes through epigenetic modification connected with recruitment of histone metylotransferase SET domain bifurcated 1 (SETDB1)." (PMID 29104587, 2017).
autism spectrum disorder (3 papers, 2020 to 2022). A spectrum of developmental disorders that includes autism, and Asperger syndrome. "In neurodevelopment, the impact of SETDB1 is crucial, as evidenced by a de novo 1q21.3 deletion present in patients with intellectual disability (ID) or typical autism spectrum disorder (ASD) that affects the SETDB1 gene, among others." (PMID 34440561, 2021).
autoimmune disease (3 papers, 2014 to 2025). A disorder resulting from loss of function or tissue destruction of an organ or multiple organs, arising from humoral or cellular immune responses of the individual to their own tissue constituents. "Beyond cancer, SETDB1 appears to be involved in immune modulation observed in autoimmune diseases such as immune thrombocytopenia (ITP), where the transcriptional levels of human ERVs correlate with those of TRIM28/SETDB1." (PMID 39945463, 2025). "Notably, ATF7IP’s repressive partners MBD1 and SETDB1 have very different knockout phenotypes, namely mild spatial learning defects and autoimmune disease in adult mice lacking Mbd1, and early embryonic lethality at 3.5 to 5.5 days post conception for the Setdb1 deletion." (PMID 25028596, 2014).
depression (3 papers, 2020 to 2025). "Loss of SETDB1 results in Htr3a overexpression, increased excitability of cortical GABAergic interneurons, and the emergence of anxiety- and depression-like behaviors in mice." (PMID 41589304, 2025). "In addition to exhibiting a reduced level of behavioral despair and anhedonia at baseline, these Setdb1 mice showed accelerated recovery from depression-like states when challenged with sub-chronic stress in the learned helplessness paradigm." (PMID 32321908, 2020). "Therefore, it would be of interest to continue functional studies in Setdb1 mice using stress-induced depression models." (PMID 32321908, 2020). "Epigenetic alterations mediated by H3K27me3 (EZH2) and H3K9me3 (SETDB1) are not unique to depression but also appear in models of schizophrenia and bipolar disorder." (PMID 41589304, 2025). "However, dysregulation of SETDB1 activity and its downstream pathway (for example, the repression of Grin2b that encodes NMDA receptor NR2B) might be involved in the progression of neuropathology of symptoms of depression under negative environmental impacts." (PMID 32321908, 2020).
diabetes (3 papers, 2021 to 2025). "SENP2 modulates diabetes-associated lipid metabolism through regulating the deSUMOylation of SET domain bifurcated 1 (Setdb1)." (PMID 40078991, 2025).
malignant pleural mesothelioma (3 papers, 2016 to 2022). A malignant neoplasm that arises from mesothelial cells in the pleura and shows a diffuse growth pattern. "It has been reported that mutated SETDB1 is widespread and occurs in most malignant pleural mesothelioma." (PMID 35656340, 2022). "The frequent SETDB1 mutation indicates that there may be a potential therapeutic target for malignant pleural mesothelioma." (PMID 35656340, 2022). "The Malignant Pleural Mesotheliomas (MPM) are characterized by a high frequency of SETDB1 mutations, resulting in a non-functional SETDB1 protein." (PMID 34440561, 2021).
mesothelioma (3 papers, 2016 to 2022). A usually malignant and aggressive neoplasm of the mesothelium which is often associated with exposure to asbestos. "KAP1/TRIM28 recruits chromatin modifiers including SETDB1, which is mutated in a subset of mesothelioma, thereby possibly also contributing to differential HERVH and HERVK expression." (PMID 36467966, 2022). "In contrast, frequent inactivation mutations of SETDB1 have been revealed in mesothelioma, an asbestos-associated, locally aggressive, highly lethal, and notoriously chemotherapy-resistant cancer." (PMID 34299035, 2021). "Frequent SETDB1 inactivation mutations indicate the diagnostic or treatment potential for SETDB1 in mesothelioma." (PMID 34299035, 2021). "On the contrary, a series of studies revealed that only mutation and inactivation of SETDB1 exist in mesothelioma, indicating that SETDB1 may play a tumour-supressing role." (PMID 34299035, 2021). "Our finding that SETDB1 had a nonsense mutation (Y249X) and the fact that another inactivating frameshift mutation (V132fs) was reported in the mesothelioma cell line ACCMESO1, led us to hypothesize that truncating mutations such as nonsense and frameshift mutations are frequent in MPM." (PMID 26824986, 2016). "Moreover, inactivation mutation of SETDB1 was found in malignant pleural mesothelioma (MPM), suggesting that it may lose function and act as a tumour suppressor in mesothelioma." (PMID 34299035, 2021). "A frameshift mutation (V132fs) producing a premature stop codon in SETDB1 was also described in the ACCMESO1 mesothelioma cell line (Cancer Cell Line Encyclopedia (CCLE) database), which suggests a potential role of SETDB1 in MPM development." (PMID 26824986, 2016).